OR51G1 (olfactory receptor family 51 subfamily G member 1)
Description:
Odorant receptor.
Synonyms: OR51G3P; OR11-29
Tractability: Antibody: UniProt places it where antibodies can reach, with medium confidence; UniProt predicts a signal peptide or a membrane-spanning region; its Gene Ontology location is reachable by antibodies, with medium confidence.
Gene: Protein-coding gene on chromosome 11 (4,923,374 to 4,924,339, reverse strand). Ensembl gene ENSG00000278870.
Subcellular location: Cell membrane
Pathways (Reactome):
Sensory Perception: Expression and translocation of olfactory receptors
Gene Ontology:
Molecular function: olfactory receptor activity; G protein-coupled receptor activity; signaling receptor activity
Biological process: cellular response to lipid; detection of chemical stimulus involved in sensory perception of smell; G protein-coupled receptor signaling pathway; system process
Cellular component: plasma membrane; membrane
Genetic constraint (gnomAD): Loss-of-function variants: 3 observed, 1.84 expected, observed/expected ratio (o/e) 1.63, 90% interval 0.59 to 1.93. That is too few expected variants to judge how well the gene tolerates losing a copy. Missense variants: 454 observed, 417.44 expected, observed/expected ratio (o/e) 1.09, 90% interval 1.01 to 1.17. Synonymous variants: 163 observed, 165.94 expected, observed/expected ratio (o/e) 0.98, 90% interval 0.86 to 1.12.
Homologues: Orthologues: chimpanzee OR51G1 (98% identical), rabbit OR51G1 (89% identical), pig OR51G1 (88% identical), mouse Or51g1 (87% identical), rat Or51g1 (85% identical), tropical clawed frog or51ao1 (46% identical). Paralogues in human: OR51G2 (61% identical), OR51L1 (53% identical), OR51A4 (53% identical), OR51A2 (52% identical), OR51A7 (52% identical), OR51M1 (52% identical), OR51I2 (52% identical), OR51C1 (51% identical), OR51B5 (50% identical), OR51V1 (50% identical), OR51B6 (50% identical), OR51I1 (50% identical), and 39 more.
Diseases named in the same sentence as OR51G1 in open-access papers:
OR51G1 is named in the same sentence as 2 diseases in open-access papers, as found by Europe PMC text mining. Sharing a sentence is not in itself a finding about the gene and the disease. The quoted sentences say what the papers report.
cognitive decline (1 paper, 2022). "OR51G1 is an olfactory receptor gene, and previous studies have reported a relationship between olfactory dysfunction and risk of cognitive decline, including AD." (PMID 35264725, 2022).
OR51G1 also shares sentences with these, for which no sentence is quoted: tumor (1 paper).